IL22 (interleukin 22)
Diseases named in the same sentence as IL22 in open-access papers (continued):
Sharing a sentence is not in itself a finding about the gene and the disease.
colitis (continued). "Furthermore, in a recent study, RA has been shown to induce IL-22 secretion by γδ T cells and innate lymphoid cells with protective effects in murine colitis models." (PMID 29124320, 2018). "However, RNA profiling analysis revealed the capacity of ABX464 to induce the expression of IL-22, a cytokine involved in colitis tissue repair, both in DSS-treated mice and in LPS-stimulated bone marrow-derived macrophages." (PMID 28687795, 2017). "Likewise, in a T-cell transfer model of colitis, transfer of IL-22−/− T cells resulted in a more severe phenotype of colitis than in mice infused wild-type T cells." (PMID 28302598, 2017). "IL-22-mediated protective effects were seen in T cell transfer colitis." (PMID 28584821, 2017). "Importantly, anti-IL-22 antibodies significantly reduced the protective effect of ABX464 on colitis in DSS-treated mice." (PMID 28687795, 2017). "In immunologically intact mice, Th17 cells also produce IL-22, a member of the IL-10 family of cytokines, which may protect against colitis." (PMID 28302598, 2017). "Our results are consistent with the previous studies showing correlation between the increase in the abundance of Prevotellaceae and the severity of microflora-transmissible colitis in NLRP6 inflammasome-deficient mice, in IL22-/- mice, and in Casp3/11-/- mice." (PMID 26727498, 2016). "Furthermore, in the TCRα KO mouse model, representing a model of UC, IL-22 gene delivery improved colitis through mucin induction and goblet cell restitution." (PMID 27645534, 2016). "By contrast, double blockade of IL-17A and IL-22 reduced colitis severity, indicating that these cytokines may play a redundant role in driving intestinal inflammation possibly through shared effects on intestinal epithelial cells." (PMID 26780670, 2016). "In this scenario, IL-22 elevated IFN-γ production, reduced IL-10 levels, and promoted neutrophil recruitment, which is likely the cause for the pathology seen in this model of colitis." (PMID 27578924, 2016). "Similarly, local delivery of the IL-22 gene attenuated the spontaneous colitis that develops in T cell receptor (TCR)-α knockout (KO) mice and that evoked by transfer of naïve CD45RBhi T cells into RAG2-/- mice." (PMID 27055194, 2016). "Moreover, DNBS-induced colitis was significantly less severe in IL-22-/- compared to wild-type mice: IL-22-/- mice infected with H. dimunta 8-days prior to the induction of colitis had negligible disease." (PMID 27055194, 2016). "In addition, it has been suggested that IL23R+ ILCs can induce colitis via an IL-22-dependent pathway." (PMID 27578924, 2016). "In contrast, IL-22 expressers from colitic mice, transferred into secondary hosts, lost reporter expression, acquired high T-bet and modest IFNγ and IL-17 expression, and induced severe colitis." (PMID 26834739, 2015). "Studies have shown that colitis can be reversed by the introduction of IL-22." (PMID 26793707, 2015). "Furthermore, it was shown that IL-23R signaling promotes innate colitis via IL-22 as neutralization of IL-22 protects mice from colitis and the adding back of IL-22 to IL-23R-deficient animals restores the disease." (PMID 25061260, 2014). "This in vivo study also found that both neutralizing the IL-22 via injections of a blocking antibody of IL-22 and treatment with the AhR antagonist, 2-metal-2h-pyrazole-3-carboxylic acid, contributed to suppression of the production of cytokine IL-22 and acceleration of the symptoms of colitis." (PMID 24905409, 2014). "IL-22-mediated protective effects were seen in the T cell transfer colitis model." (PMID 23956763, 2013). "In addition, colonic LTi-like cells constitute a substantial proportion of the IL-22-producing cells in the cLP of Rag1−/− mice, both in health and in the setting of colitis." (PMID 23750260, 2013).
colitis (continued). "Looking at IL-22, it is tempting to relate those complications to constitutive IL-22 expression by intestinal NK-like/innate lymphoid cell populations and pathogenic properties of STAT1 in human colitis." (PMID 23382730, 2013). "Similarly, colitis induced by Helicobacter hepaticus infection is promoted by IL-22 in both innate and lymphocyte replete models (authors' unpublished observations)." (PMID 23405904, 2013). "In addition, intestinal LTi cells protect against Citrobacter rodentium infection and dextran sodium sulfate (DSS)-induced colitis by secreting IL-22." (PMID 23750260, 2013). "Interestingly, an anti-inflammatory role of IL-22 in different models of colitis has been previously demonstrated." (PMID 21977228, 2011). "IL-22 is induced during certain infectious models including Salmonella enterica, Toxoplasma gondii, Citrobacter rodentium, Klebsiella pneumoniae, and in an induced model of colitis." (PMID 21347242, 2011). "IL-22-mediated protective effects are also seen in the T cell transfer colitis model." (PMID 22082127, 2011). "HQD could alleviate DSS-induced colitis through microbiota-derived indoles that activate AhR and, directly or via IL-22, drive ISC differentiation; however, this attractive mechanistic framework is not unique to HQD—probiotics or synthetic AhR agonists can exploit the same pathway." (PMID 41530817, 2026). "In addition, the expression levels of the anti-inflammatory IL-10 and IL-22 in the DSS + GMEVs group were considerably greater than in the DSS group, with this difference perhaps underlying the beneficial effect of GMEV pre-treatment for relieving colitis." (PMID 40361597, 2025). "However, in chronic inflammatory conditions like colitis, IL-22 can exacerbate disease progression." (PMID 40749055, 2025). "Therefore, IL-17A may play the dominant role in Tak1ΔM/ΔM mice to maintain the resistance against colitis, while IL-22 provides an independent and supportive function." (PMID 40749055, 2025). "In the anti-CD40 induced colitis model, which is IL-23 dependent, ILC3s are a major source of GM-CSF, which is needed for these cells to move from cryptopatches to the intestinal tissue where they produce IL-22 and initiate an inflammatory immune cascade that results in intestinal inflammation." (PMID 41194916, 2025). "Furthermore, an animal study showed that IL-23R on ILCs promotes colitis via IL-22." (PMID 40429917, 2025). "In addition, TNF abrogated IL-22-mediated mucosal repair during T cell transfer colitis." (PMID 40498001, 2025). "Additionally, the levels of Reg3γ were significantly reduced in IL‐22 KO memory‐effector transfer mice, suggesting that IL‐22 may drive colitis by inducing REG3γ, that may alter the microbiota composition and lead to dysbiosis." (PMID 38363052, 2024). "Because IL-17A and IL-22 are critical for maintaining intestinal barrier function, we asked whether C. tropicalis colonization modulates intestinal epithelial barrier function and integrity during colitis in vivo." (PMID 39462273, 2024). "However, colitis developed in Il‐23−/−Rag−/− mice only after anti‐CD40 injection, indicating that IL‐22 plasmid injections alone do not cause colitis." (PMID 38363052, 2024). "However, what was not established in this previous report was whether AhR was specifically driving these observations during I3C treatment and colitis, particularly as it related to increased IL-22 production by ILC3s and regulation of the gut microbiome." (PMID 39229279, 2024). "In agreement with the deleterious effect of IL-22 in CRC, the sensing of microbial ligands by DCs downregulates IL-22BP expression, an antagonist of IL-22, and this downregulation increases inflammation and tumorigenesis in colitis-associated colon cancer models." (PMID 37296855, 2023). "However, IL-21 may play a protective role in the DSS-induced colitis model through its induction of IL-22, a member of the IL-10 family that promotes tissue regeneration and repair." (PMID 36519841, 2023).
colitis (continued). "While exogenous administration of IL-22 ameliorates﻿ this phenotype, transferring the microbiome of IL-22 or IL-23 pathway-deficient animals to wild-type mice leads to reduced AMP and IL-22 expression in the gut and, again, increased sensitivity to chemically induced colitis." (PMID 36894983, 2023). "Hence we assumed that B. fragilis may motivate the IL-22 signaling pathway to promote intestinal mucosa regeneration and modulate intestinal flora in colitis." (PMID 37114045, 2023). "In our experiment, the results of the multiplex immunoassay showed a partial change in ILC3-associated cytokines such as IL-22 and GM-CSF, but the more noticeable difference was in ILC2-derived cytokines, including IL-10, which could modulate DSS-induced colitis through a macrophage–ROS–NO axis." (PMID 36101343, 2022). "Thus, impairment of RA signaling likely contributes to reduced Il-22 mRNA levels in colitis mice." (PMID 35889745, 2022). "In addition, CARD9 promotes the recovery of colitis by activating the IL-22 pathway." (PMID 35273921, 2022). "Taken together, these data support the notion that IL-22-mediated induction of neutrophil-active chemokines, including CXCL1 and CXCL5 is functionally important in the recruitment of CXCR2+ neutrophils, and that this pathway has an important pathogenic function in colitis." (PMID 36192482, 2022). "Therefore, more extensive studies about the effect of vitamin C on mast cells in the gut epithelium are required to clarify whether the IL-22-dependent anti-inflammatory effects of vitamin C on colitis are through mast cell regulation." (PMID 36142515, 2022). "In addition, IL-10/IL-22 double-deficient mice lacking colitis exhibited higher microbial diversity when compared to IL-10-deficient mice." (PMID 36012618, 2022). "Interestingly, IL-36 can also regulate Treg/Th9 balance and the IL-23/IL-22 network in model of colitis induced by oxazolone, indicating that IL-36γ has multiple functions in modulating antigen-presenting cell function and in regulating T cell differentiation in a mouse model." (PMID 34054828, 2021). "Additionally, there is evidence that Blastocystis modulates the immune system through IL-22 release that stimulates mucus production, alleviates colitis symptoms and induces an immune response with a predominance of the Th2 cell response, favouring an anti-inflammatory environment." (PMID 34895145, 2021). "Therefore, IL-22/occludin signal pathway is important in colitis." (PMID 33381598, 2020). "In a T cell transfer colitis model, T-bet deficient T cells promoted an exacerbated Th17 response in the gut, and T-bet-deficient CD4 T cells isolated from an inflamed colon were hyper-responsive to IL-23 in terms of STAT3 phosphorylation and IL-17 and IL-22 production." (PMID 32906785, 2020). "Therefore, IL-22/occludin signal pathway plays an important role in colitis." (PMID 33381598, 2020). "Colitis is characterized by expression of both pro-inflammatory cytokines, including tumour necrosis factor-alpha (Tnfa), interleukin 1-β (Il1b), and interleukin 17 A (Il17a), and anti-inflammatory cytokines, including interleukin 10 (Il10) and interleukin 22 (Il22)." (PMID 32042047, 2020). "Notably, the abolishment of IL-22 completely blocked the protective effect of TP5 on colitis." (PMID 31695782, 2019). "Importantly, decreased IL-18, and to a lesser extent IFNγ, production was evident in Casp11−/− mice at 2 weeks, which may be ultimately responsible for defective IL-22 production observed in these mice during both experimental colitis and CAC." (PMID 30538296, 2019). "Moreover, ILC3s are known to produce IL-22 to protect the body during Citrobacter rodentium-induced colitis, and IL-22 drives antimicrobial peptide expression and is required for the prevention of severe intestinal pathology and mortality during C. rodentium-induced colitis." (PMID 30804706, 2019).
colitis (continued). "However, the presence of microbiota provide signals for both CX3CR1+ inflammatory cells and CD11b+CD103+ DCs in the lamina propria to produce IL-23 and induce IL-22 secretion by innate lymphoid cells, thus playing a critical role in promoting mucosal healing in colitis." (PMID 28458670, 2017). "This crosstalk may also be important in the context of intestinal inflammation and following perturbation of intestinal barrier function as MNP-derived cytokines were found to regulate ILC3 production of IL-22, in addition to GM-CSF, in mouse models of colitis and human IBD patients." (PMID 29085366, 2017). "Indeed, C. rodentium infection induces a robust Th1/Th17 response with increased gene expression of IFN-γ, interleukin-12 (IL-12), IL-17, and IL-22 while acute DSS colitis activates a predominant Th1 response but with upregulation of several Th2 cytokines including IL-10." (PMID 27046199, 2016). "Therefore, although IL-22 expression is increased during colitis, IL-22 is hypothesized to exert protective functions via activation of Stat3 in the intestinal epithelium." (PMID 25799189, 2015). "Conversely, and opposed to the tissue-protective effects described for IL-17A and IL-22, it has been reported that IL-17F-deficient mice develop milder DSS-induced colitic symptoms than wild-type animals, thus suggesting that IL-17F exacerbates inflammation in this experimental model of colitis." (PMID 25101191, 2014). "IL-23, which promotes Th17 cell development, as well as IL-17 and IL-22 produced by the Th17 cells plays essential roles in various inflammatory diseases, such as experimental autoimmune encephalomyelitis, rheumatoid arthritis, colitis, and Concanavalin A-induced hepatitis." (PMID 23956763, 2013). "This hypothesis is supported by studies performed by Leppkes and colleagues showing that transfer of IL-17A-, IL-17F-, or IL-22-deficient T lymphocytes into RAG1-null mice induces severe colitis that is indistinguishable from that caused by wild-type cells." (PMID 22082127, 2011). "In our study, we also found that the IEC-specific deletion of STAT3 (Villin-Cre STAT3fl/fl) reduced the secretion of anti-inflammatory cytokines IL-10 and IL-22 and augmented epithelial erosions and mucosal barrier disruption after DSS-induced colitis." (PMID 39773987, 2025). "This metabolic shift enhanced IL-17A and IL-22 production by ILC3s, thereby strengthening the intestinal barrier and relieving the disease in a DSS-induced colitis model." (PMID 40498001, 2025). "In this study, we investigated the mechanisms by which TH17 cells and their cytokines (IL-17A and IL-22) control local inflammation and render resistance to DSS-induced colitis and CRC development." (PMID 40749055, 2025). "In summary, these findings demonstrate that L. paracaseiL21 and its postbiotic mitigate colitis by enhancing SCFA-mediated activation of AhR/HIF1α signaling, thereby promoting IL-22-dependent mucin synthesis and goblet cell regeneration." (PMID 40806121, 2025). "On the contrary, in other models of colitis (such as anti-CD40 antibody-induced acute colitis), the inflammation is driven by the IL-22 produced by ILC3s." (PMID 40002718, 2025). "High indole-3-lactic acid (ILA) production is a key tryptophan metabolic characteristic of L. plantarum which activated AHR downstream signaling (such as CYP1A1, IL-22, and STAT3) to alleviate colitis." (PMID 41019044, 2025). "In summary, our studies demonstrate that DCA promotes a metabolic program that regulates T cell production of IL-10 and IL-22, and that DCA treatment inhibits colitis development." (PMID 41321963, 2025). "A novel anti-colitis mechanism of oligofructose (FOS) promotes the production of indole-3-acetic acid (IAA) and indole propionic acid (IPA) to trigger AhR/IL-22 axis activation by alleviating intestinal dysbiosis and modulating microbial tryptophan metabolism." (PMID 41019044, 2025).
colitis (continued). "ILC3-derived IL-22 can facilitate intestinal epithelial restitution after tissue destruction via inducing cell proliferation and maintaining intestinal epithelial stem cells (ISCs), which might be involved in injury reduction of colitis and other intestinal inflammatory diseases." (PMID 41467015, 2025). "B. fragilis has been shown to promote colonic mucosa regeneration in colitis via promotion of IL-22 secretion by ILC3s, but Bacteroides sphingolipids have also been shown to exacerbate colitis by inhibiting ILC3-derived IL-22 production." (PMID 41550925, 2025). "In TNBS mice colitis, AHR ligands NPD-0414-2 and NPD-0414-24 had a modulatory influence on the production of IFN-γ and IL-22, by which AHR can maintain an anti-inflammatory effect in the gut by suppressing pro-inflammatory cytokines." (PMID 38542367, 2024). "Our findings demonstrate that USP28 is essential for T cell functionality and protects mice from acute DSS-induced colitis by regulating STAT5 signaling and IL22 production." (PMID 39076972, 2024). "In fact, they suggest that Lactobacillus reuteri induced LPLs to secrete IL-22 through AhR and then activated STAT3 phosphorylation to counteract epithelial damage in DSS-induced colitis mice." (PMID 39517263, 2024). "In both acute and chronic DSS-induced colitis settings, cytokine levels were comparable between USP28-/- and USP28+/+ mice and the level of IL22 was still increased in USP28-/- mice compared to control mice." (PMID 39076972, 2024). "Collectively, our data show that the IL-22-dependent STAT3-B3GALT5 pathway and MATH1+ progenitor cell-mediated intestinal regeneration protected from DSS colitis." (PMID 38733584, 2024). "Inhibitory function was further verified by competition ELISA, HEK-Blue IL-22 reporter cells, and murine dextran sulfate sodium (DSS)-induced colitis." (PMID 39354587, 2024). "Our findings suggest that LCN2 specifically regulated ILC3s, particularly the NKp46+ILC3 subgroup, to secrete IL-22 and IL-17A by targeting GPX4, thereby exerting a protective effect on colitis." (PMID 39300068, 2024). "We found that the activation of Wnt/β-catenin signaling not only leads to a dramatic reduction of ILC3s but also promotes the dysfunction of ILC3s with reduced expression of IL-22, MHC-II, IL-2, GM-CSF, which further aggravates the DSS-induced colitis in mice." (PMID 38561332, 2024). "In their novel work, they found that TNF interferes with the tissue-repair program by inducing a soluble natural IL-22 antagonist (IL-22Ra2; IL-22BP) in the colon and abolishes IL-22/STAT3-mediated mucosal repair during colitis." (PMID 39795980, 2024). "Am06 displays a consistent capability for inducing RA synthesis and IL-22 secretion, much like the Akk BAA-835 strains, further bolstering the significant role of RA synthesis in reducing colitis by Akk." (PMID 39734222, 2024). "Pretreatment with cefoxitin, a broad-spectrum antibiotic, exacerbates CR-induced colitis and lethality in specific-pathogen-free (SPF) Il22-/- and Rag1-/- mice." (PMID 39630719, 2024). "In contrast, treatment of mice with an AhR antagonist reduced IL-22 production and increased the severity of inflammation in a TNBS-induced mouse colitis model." (PMID 39113799, 2024). "The AhR antagonist StemRegenin 1 essentially abrogated the ameliorative effect of 5HIAA on colitis, as reflected by body weight, DAI, colon length, serum levels of IL‐22 and IL‐10, and colon histology." (PMID 38882491, 2024). "IL-22 level was significantly reduced in DSS-induced colitis mice, and BTW treatment significantly increased the concentration of IL-22 in colitis mice." (PMID 38974042, 2024). "In contrast, treatment with an AhR antagonist reduced IL-22 levels and exacerbated inflammation in a murine model of TNBS-induced colitis." (PMID 39767818, 2024).